FGFR3 (fibroblast growth factor receptor 3)
Diseases named in the same sentence as FGFR3 in open-access papers (continued):
Sharing a sentence is not in itself a finding about the gene and the disease.
cancer (418 papers, 2003 to 2026). A tumor composed of atypical neoplastic, often pleomorphic cells that invade other tissues. "Proteins like RET (enriched in JAK-STAT signaling) and FGFR3 (linked to pathways in cancer) are already targeted by approved therapies in other malignancies, suggesting rapid repurposing potential for PCa." (PMID 41247789, 2025). "Numerous emerging therapies are aimed at more effectively treating and targeting cancers associated with FGFR3 mutations." (PMID 40943615, 2025). "Among these, we observed high-frequency variants across 25 cancer-related genes, with complete penetrance notably found for FGFR3 (rs7688609, COSM4533173) and PDGFRA (rs1873778, COSM7410554)." (PMID 41567639, 2025). "FGFR3 gene transcript (circRNA product) is over expressed in bladder cancer and associated with increased cancer cell proliferation and migration." (PMID 39118085, 2024). "Previous studies have reported that the inhibition of FGFR3 caused growth inhibition and reduced the proliferation of cancer cells." (PMID 36855119, 2023). "Gain-of-function mutations in FGFR3 contribute to the pathogenesis of cancers and skeletal dysplasias, making it a vital therapeutic target." (PMID 37824212, 2023). "Potential disease targets include FGFR3-related skeletal dysplasias and also other conditions caused by excessive FGFR3 function, such as cancers and seborrheic keratoses." (PMID 37824212, 2023). "FGFR3 (Fibroblast growth factor receptor 3) gene encodes a receptor involved in a wide array of pathways known to play a significant role in cancer." (PMID 35503718, 2022). "According to the American Joint Committee on Cancer’s 8th edition, FGFR3 expression is associated with a lower-grade tumor and a lower risk of cancer progression." (PMID 36359539, 2022). "When chemotherapy is administered to patients with advanced cancer, FGFR3 gene alterations are associated with less favorable outcomes." (PMID 36359539, 2022). "It was demonstrated that ectopic activation of FGFR3 is associated with several cancers, including multiple myeloma, cervical cancer, and BC." (PMID 36361996, 2022). "Patients included had FGFR-3 mutated or wild-type cancer, and all of them progressed on platinum-based or combined therapy." (PMID 35326568, 2022). "Suppression of FGFR3 activation is sufficient to reduce the survival and proliferation of carcinoma cells harboring FGFR3 mutations." (PMID 35494629, 2022). "In this analysis, 234 FGFR3 mutations were detected in various cancer types of TCGA and distributed across different FGFR3 functional domains." (PMID 34160364, 2021). "Other cancers that had dominant FGFR3 mutations but were at relative lower alteration frequency contained UCEC (6.81%), SKCM (5.18%), STAD (3.64%), HNSC (3.63%), COADREAD (3.37%), KIRP (2.47%) and MESO (1.38%)." (PMID 34160364, 2021). "In recent years, along with improvements in clinical genetic testing techniques in oncology, more FGFR3 gene alterations are discovered and implicated in a wide range of cancers." (PMID 34160364, 2021). "We observed 234 FGFR3 somatic mutations across 32 TCGA cancers, among these mutations, 42 FGFR3 mutations belonged to fusion." (PMID 34160364, 2021). "The total mutation frequency of FGFR3 was 2.13% for all cancer samples (234/10,967) across various cancer types of TCGA." (PMID 34160364, 2021). "Collectively, ATP-dependent BRG1/BRM-associated factor (BAF), mutation in chromatin remodeling complex SWI/SNF that dysregulates chromatin remodeling, and the cancer-associated transcription factors also result in FGFR3 overexpression." (PMID 34502435, 2021).
cancer (continued). "Here, we further analyzed the combined alterations of FGFR3 including mutation and CNVs across different cancer types." (PMID 34160364, 2021). "Some cancer types had dominant mutations but rare CNVs of FGFR3 such as SKCM, COADREAD, KIRP, and MESO." (PMID 34160364, 2021). "Several cancer-associated genes—Fibroblast Growth Factor Receptor-3 (FGFR3), phosphatidylinositol-4,5-bisphosphate 3-kinase catalytic subunit alpha (PIK3CA) and N-ras proto-oncogene (NRAS) are identified as mutant in HT1197 when compared to HT137642." (PMID 33790357, 2021). "FGFR3, which supported cancer-associated fibroblast (CAF) survival and activation, exhibited significantly higher expression in the PD-L1-low-actived and PD-L1-low-exhausted groups compared with the other groups." (PMID 34059019, 2021). "Among American Joint Committee on Cancer (AJCC) 8th edition T1 tumors, FGFR3 expression is associated with lower grade tumor and lower risk of cancer progression." (PMID 33224141, 2020). "FGFR3 somatic mutations or excessive FGFR3 protein expression can lead to the development of a variety of malignant tumors." (PMID 33381388, 2020). "In studies involving the detection of fibroblast growth factor receptor 3 (FGFR3) mutations from urine samples of cancer patients, NGS was proven to be much more sensitive than PCR-based methods for detection." (PMID 32685026, 2020). "Interesting FGFR3 mutations are typically associated with low-grade cancers and favorable prognoses, and patients harboring these mutations had WHO grade I tumors, with no recurrence in our cohort." (PMID 31565188, 2019). "Receptor tyrosine kinase FGFR3 is involved in many signaling networks and is frequently mutated in developmental disorders and cancer." (PMID 29478821, 2018). "Using the publicly available ENCODE data for three different cancer cell lines, we designed primers binding to two potential enhancers, the promoter and an intragenic region of FGFR3." (PMID 29463565, 2018). "We further extended this in vitro analysis to a panel of over 20 cancer mutations in the kinase domain of FGFR3 some of which overlap with mutations found in developmental disorders." (PMID 29478821, 2018). "Given this unexpected finding, we rereviewed all 41 FGFR3 mutations in our sporadic cohort of 82 UTUCs and identified two carcinomas with an FGFR3 R248C mutation." (PMID 30854504, 2018). "In contrast to the activation of FGFR3 by mutation, amplifications of FGFR3 have been rarely described in cancers." (PMID 28030802, 2017). "In contrast, mutations in FGFR3 are present in both earlier and latter stages but with higher frequencies (about 80%) at early stages of cancer initiation and are regarded as a distinct path in urothelial tumorigenesis." (PMID 29262532, 2017). "Two carcinomas each harbored a missense mutation in the fibroblast growth factor receptor 3 (FGFR3) and the receptor tyrosine kinase KIT." (PMID 27844328, 2017). "The panel includes about 47% of all intracellular residues reported to be mutated in FGFR3 in cancer." (PMID 26992226, 2016). "We used these tools for analysis of all reported intracellular FGFR3 cancer mutations and also included some common mutations found in other FGFRs or in bone dysplasia." (PMID 26992226, 2016). "The residue corresponding to R669 in FGFR3 is conserved and also mutated in all other FGFRs in cancer as well as in FGFR2 in bone dysplasia." (PMID 26992226, 2016). "N540 FGFR3 mutations in bone dysplasia reflect the overall picture of FGFR1-4 mutations in cancer with the replacement N540K being the most frequently observed." (PMID 26992226, 2016). "Our data reinforce the importance of frequently observed mutations at positions corresponding to FGFR3 N540 and K650 that occur in different FGFRs and in a range of cancer types as well as in bone dysplasia." (PMID 26992226, 2016).
cancer (continued). "Basal cancers were enriched with squamous histopathological features, whereas luminal cancers were enriched with papillary histopathological features and activating DNA mutations and fusions involving fibroblast growth factor receptor-3 (FGFR3)." (PMID 27845906, 2016). "Two frequently mutated positions (“hotspots”) were identified in FGFR3 KD in cancer (K650 and G697) and a third (corresponding to N540 in FGFR3) was revealed only when considering all FGFRs." (PMID 26992226, 2016). "Activating mutations in fibroblast growth factor receptor 3 (FGFR3) have been identified in multiple types of human cancer and in congenital birth defects." (PMID 27056048, 2016). "We assessed the mutational status of FGFR3 and other cancer-relevant genes in samples from cohort using a custom allele-specific PCR panel." (PMID 27846280, 2016). "Among FGFR kinase domain (KD) cancer mutations, another FGFR3 activating mutation, K650E, has been most extensively characterized." (PMID 26992226, 2016). "When positions of FGFR3 cancer mutations are highlighted in the FGFR KD structure, one hot spot (K650) and 9 other residues are present within the A-loop while R669 is in its vicinity." (PMID 26992226, 2016). "FGFR3 mutations are reported in up to 50% of cancers of all stages from the lower and upper urinary tract with p.S249C being the most common mutation, found in 61% of cases." (PMID 27669755, 2016). "Active mutations of FGFR2 or FGFR3 are common in various cancers, whereas the oncogenic impetus of FGFR1 results mainly from either gene amplification or overexpression of wild-type receptor." (PMID 26201468, 2015). "Mapping of the FGFR2/FGFR3 cancer mutations onto the crystal structures and conformational dynamics profiles demonstrated that mutations are broadly distributed in the kinase domain occupying different segments." (PMID 24817905, 2014). "Our findings suggest TAK1 as a potential therapeutic target for FGFR3-associated cancers, and other malignancies in which TAK1 contributes to constitutive NFκB activation." (PMID 24466111, 2014). "Low-grade NMI cancers arise through regional deletion of chromosome 9, mutation of FGFR3 (Fibroblast growth factor receptor), and H-RAS4." (PMID 25142434, 2014). "We took a systematic approach to gaining a better understanding of FGFR3 signaling in associated cancers through the identification of new FGFR3 protein interactions using a yeast two hybrid (Y2H) assay." (PMID 24466111, 2014). "In cancers, activating somatic mutations of FGFR3 were first characterized in bladder cancer and cervix cancer." (PMID 23902722, 2013). "For example, the activating somatic mutations in the FGFR3 gene appear to be bladder specific, and a much lower frequency of the mutations of the FGFR3 has been observed in other cancer sites." (PMID 17088904, 2006). "Current treatments for cancers associated with FGFR3 focus on inhibiting its signaling pathways." (PMID 40943615, 2025). "However, FGFR3 mutations are permissive for the development of carcinoma in situ or high-grade tumors when combined with SV40 large T antigen, PTEN loss, or the carcinogen N-butyl-N-(4-hydroxybutyl)nitrosamine (BBN)." (PMID 38226620, 2024). "These evidences suggest convincing role of FGFR3 in cancers predispositions and disease outcome." (PMID 38635549, 2024). "Furthermore, study results demonstrated that BC expressing decreased FGFR3 protein has a higher risk of cancer progression of HG tumors." (PMID 39219882, 2024).
cancer (continued). "However, only 2/7 (29%) carcinomas with FGFR3::TACC3 fusion (excluding a case with concomitant FGFR3 mutation) had elevated FGFR3 mRNA expression." (PMID 39596194, 2024). "The compounds identified by this approach may have applications as therapeutics for FGFR3-associated cancers and skeletal dysplasias." (PMID 37824212, 2023). "Furthermore, TERT promoter mutations cooperate with TPP1 promoter nucleotide changes to lengthen telomeres and with mutated BRAF and FGFR3 oncoproteins to enhance oncogenic signalling in cancer cells." (PMID 38033865, 2023). "FGFR3 had an inverse association with PD-L1 in human cancer tissues." (PMID 36733484, 2023). "It was previously found that FGFR3 was associated with the occurrence and progression of cancer." (PMID 37444485, 2023). "Mutations on FGFR3 or FGFR2 genes are usually associated with the presence of cancer." (PMID 35337093, 2022). "Due to frequent mutations in certain cancers, FGFR3 is considered an oncogene." (PMID 36422592, 2022). "Two carcinomas harboured a missense mutation in FGFR3 or KIT (p.L576P, p.Y823S)." (PMID 35884448, 2022). "However, mutations that were distributed in the functional classes took up a major portion of FGFR3 mutations in several cancers such as BLCA, LUSC, HNSC, KIRP, and CESC." (PMID 34160364, 2021). "Furthermore, additional driver mutations such as in MYC, BCL2, MMSET and FGFR3 are considered as important driver mutations in the development of cancer." (PMID 33572851, 2021). "Additionally, the survival association between FGFR3 aberration patterns and prognosis in distinct cancer types was conducted to explore its potential therapeutic implication." (PMID 34160364, 2021). "FGFR3 abnormal expression, methylation patterns, alteration frequency, mutation location distribution, functional impact, and prognostic implications differed greatly from cancer to cancer." (PMID 34160364, 2021). "Moreover, the location distribution of FGFR3 mutations differed greatly across different TCGA cancers." (PMID 34160364, 2021). "MFGR1877S binds to FGFR3 with a high affinity to competitively inhibit native ligand binding and prevent receptor dimerization not only in cells with wild-type FGFR3 but also in cells with the most prevalent cancer-associated mutants of FGFR3." (PMID 34502435, 2021). "For example, luminal cancers that tend to be enriched in activating mutations in FGFR3 may better respond to FGFR3 inhibiting agents." (PMID 32069881, 2020). "The most common FGFR3 point mutation found across cancer types is S249C in which the extracellular domain cysteine substitution leads to the formation of a disulphide bond between receptor monomers resulting in ligand-independent constitutive dimerization and activation." (PMID 32370101, 2020). "A FGFR3 activation mutation was associated with increased metastasis in many types of cancer." (PMID 31619201, 2019). "Moreover, we have established that an infrequent cancer mutation corresponding to R669G in FGFR3, also found in bone dysplasia, greatly enhances kinase activity of FGFR." (PMID 26992226, 2016). "However, since high levels of FGFR3 expression, associated with a cancer-related mutation, were described in SK-N-MC cells, we analyzed tyrosine phosphorylation of this receptor by western blotting which confirmed the roneparstat-induced inhibition." (PMID 27374103, 2016). "Due to frequent mutations in certain cancers, FGFR3 gene is considered as an oncogene." (PMID 23902722, 2013). "For example, Fibroblast Growth Factor Receptor 3 (FGFR3) mutations have been confirmed as potent oncogenic drivers in several cancers, and FGFR3 inhibitors may be a novel therapeutic strategy for patients with FGFR3-altered cancer." (PMID 37848933, 2023).
cancer (continued). "For example, antibody-based targeting of FGFR3 with R3Mab, an antagonistic anti-FGFR3 mAb capable of blocking ligand binding and receptor dimerisation, was tested in Ba/F3 mouse cells transfected with the cancer-associated mutants S249C, Y375C, R248C, G372C, and K652E." (PMID 34068816, 2021). "Thus, the cell line can be used for developing methods for early diagnosis, for investigating new targeting therapy including ARID1A and FGFR3, and for examining the involvement of ARID1A and FGFR3 mutation in the development, survival, and progression of cancer." (PMID 33143664, 2020). "Interestingly, we identified a number of mutations in non-NF2 genes, including a hotspot TERTp c.−124: G > A mutation that may be related to poor prognosis and FGFR3 mutations that may represent biomarkers of a favorable prognosis as reported in other cancers." (PMID 31565188, 2019). "In addition, the landscape of the somatic mutations of PIK3CB and FGFR3 could be an indication that their inactivation might promote cancer progression." (PMID 28569218, 2017). "Similarly, inhibition of FGFR3 can induce cell cycle arrest and/or apoptosis in UC both in vitro and in vivo, providing validation that FGFR3 and downstream signaling pathways represent potentially relevant therapeutic targets for the treatment of FGFR3-associated cancers." (PMID 24466111, 2014). "Functionally, the FGFR inhibitor erdafitinib suppressed cell proliferation and migration, and FGFR3 silencing also markedly reduced proliferation, migration, invasion, and colony formation in cancer cell lines." (PMID 41228379, 2025). "Specifically, among high-risk, BCG-unresponsive NMIBC patients (particularly those with carcinoma in situ) harboring FGFR3/2 alterations, erdafitinib has exhibited favorable and durable efficacy." (PMID 41438986, 2025). "These FGFR3 inhibitors, along with Covalent Pan-FGFR Inhibitors and antibodies, provide confidence in the current treatment options for FGFR3-driven cancers." (PMID 40943615, 2025). "For HPV-associated SNSCC with matched normal DNA the most frequently mutated COSMIC cancer driver genes included KMT2D (4/12 patients, 33%), FGFR3 and KMT2C (3/12 patients, 25%), GOLGA5, TET1, and ARID1B (2/12 patients, 16.7%)." (PMID 40500270, 2025). "With the patient’s consent, a cancer gene panel test was performed, which identified FGFR3::TACC3 fusion (F17*; T4) and FGFR3 amplification (copy number = 10)." (PMID 40417325, 2025). "In the head and neck, only limited studies are available on the prevalence and clinicopathological characteristics of carcinomas harboring FGFR3::TACC3 fusions." (PMID 39387893, 2025). "Recognition of more cases is mandatory to verify the existence of a distinctive FGFR3::TACC3-driven carcinoma type and to address the role of targeted therapy in these poorly characterized tumors." (PMID 39387893, 2025). "We evaluated the expression levels of FGFR3 in various fetal cancers and their related normal tissues through the Expression Atlas." (PMID 38635549, 2024). "This is in line with a recent study that identified the E3 ubiquitin ligase NEDD4 as a key factor for PD-L1 degradation in FGFR3-activated cancer, providing a mechanistic link for potential drug combinations in the future." (PMID 38473263, 2024). "We found that a small number of genes (e.g., RET, RECQL4, CUX1, FGFR4, PIK3R1, FGFR3, and GNAS) had some co-occurring variants per patient in different cancer types." (PMID 38637555, 2024). "Concerning gene expression results compared to the BBN induced cancer group, FGFR3 and HRAS (oncogenes) showed strong down-regulated expression levels in both BBN treated with artemisinin group and BBN + cisplatin group pre-treated by artemisinin." (PMID 39118085, 2024). "In aggregate, our work reports a tractable model of FGFR3S249C-driven papillary, high-grade, NMIBC with high penetrance and that reflects the cancer biology and immunobiology of FGFR3-driven human UC." (PMID 38226620, 2024).